SLC2A9 (solute carrier family 2 member 9)
Diseases named in the same sentence as SLC2A9 in open-access papers (continued):
Sharing a sentence is not in itself a finding about the gene and the disease.
gout (continued). "Significant association with gout was found for rs734553 and rs6855911 located in intron 7 of SLC2A9, even after correction for multiple testing (ten SNPs) with pcorr = 5.6*10−6 and pcorr = 1.1*10−6, respectively." (PMID 19890391, 2009). "We were able to confirm significant association between gout and SNPs in two established genes, namely SLC2A9 (rs734553 and rs6855911) and ABCG2 (rs2231142)." (PMID 19890391, 2009). "Variants in the non-coding region of SLC2A9 are associated with gout and uric acid levels in several human populations." (PMID 18989453, 2008). "The gene-based analysis identified SLC2A9 as the most significant gene linked to gout." (PMID 41075270, 2025). "Four CpG sites in SLC2A9 have a significant causal effect on serum uric acid levels and/or gout." (PMID 41311848, 2025). "SLC2A9’s additional associations with purine metabolism further highlight that neurological dysfunctions and gout may be linked to specific biochemical abnormalities in purine metabolism." (PMID 41075270, 2025). "Additionally, the significant causal effect of CpG cg03725404 in SLC2A9 has been proven to be associated with gout." (PMID 41311848, 2025). "We, therefore, examined whether MetS could also account for the association between polymorphism SLC2A9 rs3733591 and gout." (PMID 38689651, 2024). "A comprehensive examination spanning the entire SLC2A9 locus would have been imperative to ascertain whether rs3733591 ranks among the primary SNPs associated with gout and serum urate levels at this locus." (PMID 38689651, 2024). "Understanding the discovery, potential causality, and linkage disequilibrium (LD) patterns of rs3733591 and other variants within the SLC2A9 gene is crucial for elucidating their roles in gout susceptibility and metabolic syndrome, as well as their interactions with environmental factors." (PMID 38689651, 2024). "ABCG2 and SLC2A9 were also identified as mQTL of uric acid, the causative agent of gout." (PMID 36582826, 2023). "In addition, SLC2A9 SNPs affect gout caused by HPRT deficiency and the therapeutic response of allopurinol." (PMID 35922835, 2022). "The missense variants (rs16890979) of SLC2A9 showed an association with uric acid and gout." (PMID 35813212, 2022). "SLC2A9 rs3733591 (Arg265His) variant increases the risk of gout." (PMID 35922835, 2022). "Moreover, the CC genotype of SLC2A9 SNP rs1172228 in gout patients is significantly associated with renal calculi in Malaysian population." (PMID 35922835, 2022). "The genetics of hyperuricemia, which is universally accepted to be the cause of gout, involves genes such as SLC2A9 (encodes for GLUT9), SLC22A12 (encodes for URAT1), SLC22A13 (encodes for OAT4) and ABCG2; these are mostly involved in uric acid reabsorption and secretion." (PMID 35456363, 2022). "The results revealed that the variants exhibited protective effects against developing gout, namely rs3733589 (SLC2A9), rs3775948 (SLC2A9), rs1014290 (SLC2A9), rs3109823 (ABCG2), rs2622604 (ABCG2), rs6532055 (ABCG2), rs72554040 (ABCG2), rs671 (ALDH2), rs78069066 (MAPKAPK5), and rs77768175 (HECTD4)." (PMID 36221101, 2022). "SLC2A9 genetic polymorphisms other than rs3733591 resulted in a decrease in gout susceptibility, but only the rs3733591 genetic polymorphism was related to increasing gout susceptibility in the opposite direction." (PMID 36557230, 2022). "In addition to replicated associations between DNA methylation and serum urate, our study reveals significant causal effects of DNA methylation at some CpGs of SLC2A9 on serum urate and gout." (PMID 34887389, 2021). "In the non-gout cohorts, of 30 genetically-independent serum urate-associated genetic variants chosen as having the top effects by GWAS evaluated, the SLC2A9 rs12498742 variant was the largest, with PAFs ranging from 28.5 to 32.1% and AAFs from 22.0 to 23.5%." (PMID 33663556, 2021).
gout (continued). "However, the missense variant (p.Val253Ile, rs16890979) of SLC2A9 has been reported both as a protective SNP for gout and in lower UA levels." (PMID 34572357, 2021). "The rs734553 (G > T) in SLC2A9 is an intronic polymorphism that could result in an increased susceptibility to develop HU, gout, and diabetes due to altered transporter affinity." (PMID 33810064, 2021). "However, recent studies have demonstrated that SLC2A9 transports uric acid, and that genetic mutations in SLC2A9 have been linked to hyperuricemia and gout." (PMID 34572357, 2021). "The CpG cg03725404 at SLC2A9 showed a significant causal effect on gout (p < 1.9E–3 = 0.05/27)." (PMID 34887389, 2021). "However, consistent with the findings of other studies, our data suggest that p.V282I and c.1002+78A>G (SLC2A9) reduce the risk of gout, while p.N82N (SLC22A12) increases the risk." (PMID 32759716, 2020). "For SLC2A9, rs6855911, rs6449213 and rs7442295 could significantly lower risk of gout (OR1 of 0.35–0.38 and OR2 of 0.65–0.69) and serum urate (MD1 of − 54.30 to − 49.29 and MD2 of − 20 .65 to − 18.34) in Caucasians." (PMID 33087043, 2020). "Likewise, most SLC2A9-SNPs (i.e., rs1014290, rs6449213, rs6855911, rs7442295, and rs12510549) showed significantly lower risk of gout by about 25–65% in Asians and/or Caucasians, except for rs6855911 which was not significant in Asians." (PMID 33087043, 2020). "ABCG2 SNPs rs2231142 (Q141K) and rs10011796 and, for comparison, the SLC2A9 SNP rs11942223 were tested for allelic association with (a) gout in the presence of HU (gout vs. HU), (b) gout per se (gout vs. all controls), (c) HU (HU vs. NU) and, (d) serum urate levels in controls." (PMID 32164793, 2020). "Furthermore, SLC2A9-SNPs (i.e., rs1014290, rs6449213, rs6855911, rs7442295, and rs12510549) significantly lowered the risk of gout in Asians and/or Caucasians." (PMID 33087043, 2020). "In our study, SLC2A9 had a large effect on gout risk in both men and women." (PMID 30626429, 2019). "Previous research suggested that the human SLC2A9 or URAT1 variants might affect the responses to allopurinol treatment in gout patients." (PMID 31367212, 2019). "This may have affected the power to detect sex-specific differences in gout risk for the SLC2A9 variant." (PMID 30626429, 2019). "For all definitions tested, ABCG2 and SLC2A9 were associated with gout at genome-wide significance." (PMID 28793914, 2017). "An epidemiological observational study also investigated the hypothesis that simple sugar (in the form of SSBs) interacts with the SLC2A9 genotype in influencing serum urate levels and the risk of gout." (PMID 25889045, 2015). "As ABCG2 and SLC2A9 are the two major genetic risk factors for gout, we wished to examine whether variation in ABCG2 also contributes to serum urate responses to a fructose load." (PMID 24476385, 2014). "We have recently reported that variation in the other major genetic risk factor for gout, solute carrier family 2, facilitated glucose transporter member 9 (SLC2A9), influences serum urate and fractional excretion of uric acid (FEUA) responses to a fructose load." (PMID 24476385, 2014). "In summary, the loss of several kilobases of DNA in close proximity to SLC2A9, a known uric acid transporter and a candidate gene for gout, presents a biologically plausible mechanism for regulation of SLC2A9 expression and modulation of serum uric acid concentrations." (PMID 25007794, 2014). "This would be considered an unexpected response for a hyperuricemia/gout risk allele, and differs to that observed with SLC2A9 where the presence of the protective allele is associated with a smaller change in serum urate compared to those without the protective allele." (PMID 24476385, 2014). "Therefore, it was of special interest that the SLC2A9 SNPs rs13124007 and rs6850166 were associated with both gout susceptibility and gout phenotype." (PMID 22393348, 2012).
gout (continued). "Recently, genome-wide association (GWA) studies have identified single nucleotide polymorphisms (SNPs) in the SLC2A9 gene (solute carrier family 2, member 9 gene), a putative glucose transporter, which are strongly associated with serum UA concentrations and gout." (PMID 19503597, 2009). "Furthermore, we had indication for gender interaction, as separate analyses in females and males revealed association with gout for both SLC2A9 SNPs, whereas ABCG2 SNP rs2231142 only showed significant association in males, but not in females." (PMID 19890391, 2009). "However, consistent with previous results, two variants of SLC2A9 gene (p.V282I:rs16890979 and c.1002 + 78A > G:rs6823877) may be protective factors of gout." (PMID 35922835, 2022). "Therefore, SLC2A9 mutations may mediate the onset of gout and can become a target for the treatment of gout." (PMID 35281005, 2022). "The most recent review of SLC2A9 included 13 studies indicating that rs6449213 (C versus T), rs16890979 (T versus C) and rs1014290 (C versus T) significantly decreased the risk of gout whereas rs3733591 increased the risk of gout only in Asian and Maori populations and Solomon Islanders." (PMID 33087043, 2020). "The percentage of males might be a potential source of heterogeneity in the effects of ABCG2 and SLC2A9 on gout, since the risk or protective effects were consistently stronger in men; this may indicate sex-specific differences in pathological mechanisms or in the handling of urate." (PMID 33087043, 2020). "In addition, SLC2A9 rs16890979 showed possible associations with gout and hyperuricemia." (PMID 30189835, 2018). "In recent years, both ABCG2 and SLC2A9 have been attempted to use as drug targets to treat hyperuricemia and gout." (PMID 41075270, 2025). "A cross-ancestry meta-analysis of GWAS cohorts of European (EUR) or East Asian (EAS) descent identified single-nucleotide polymorphisms (SNPs) in SLC2A9 (uric acid: rs3775948; gout: rs4697701) and ABCG2 (gout: rs2622621) at single-variant resolution." (PMID 41311848, 2025). "SLC2A9 and ABCG2 are major genetic loci associated with uric acid and gout across multiple ancestral populations." (PMID 41311848, 2025). "The genes ABCG2 and SLC2A9 were found to be the major genetic factors governing gout in Taiwan (Province of China)." (PMID 40535434, 2025). "Cross-ancestry fine-mapping has identified ancestral and functional variants in SLC2A9 or ABCG2 that exhibit primate-specific regulatory effects on uric acid and gout." (PMID 41311848, 2025). "In this study, we also investigated ABCG2 and SLC2A9 in participants with gout and asymptomatic hyperuricemia." (PMID 38397902, 2024). "Previous GWAS using participants with gout and asymptomatic hyperuricemia detected the loci of genes encoding urate transporters (ABCG2 and SLC2A9) as genetic factors aggravating normouricemia into gout." (PMID 38397902, 2024). "Human genomic studies have identified many urate transporter genes, including ABCG2, SLC22A12, SLC2A9, and OAT4 as risk factors for gout by conducting genome-wide analyses and meta-analyses." (PMID 36139553, 2022). "The involved genes were ABCG2, SLC2A9, PKD2, ZNF518B, ALDH2, HECTD4, and MAPKAPK5 in the phenotype of gout; and only gene SLC2A9 was found in the AH phenotype." (PMID 36221101, 2022). "Another meta-analysis of GWASs on serum urea salt concentrations and gout in African Americans found genome-wide significance at three loci (SLC2A9, solute carrier family 2 member 12 (SLC2A12), and SLC22A12)." (PMID 35813212, 2022). "The alpha kinase 1 variant in combination with the ABCG2 SNP (rs2231142), the SLC2A9 SNP (rs1014290), or the SLC22A12 SNP (rs475688 and rs3825016) is linked to gout in the recessive model." (PMID 35813212, 2022). "We performed a large GWAS to explore the genetic variants and PRS relating to gout and AH in males, and we found that the variants located in genes ABCG2 and SLC2A9 were the major genetic factors governing gouty attack and hyperuricemia." (PMID 36221101, 2022).
gout (continued). "SLC2A9 is the most frequently reported gene associated with SUA levels, along with ABCG2, in GWAS studies of hyperuricemia and gout." (PMID 34572357, 2021). "For SLC2A9, effect sizes and variance explained were lower in the gout cohort, but some confidence intervals were overlapping." (PMID 33663556, 2021). "Intronic SNPs (rs4529048, rs7674711, and rs11936395) of SLC2A9 have been associated with both increased SUA levels and increased risk of gout." (PMID 34572357, 2021). "In the gout cohort, diet, BMI, SLC2A9 rs12498742 and ULT PAFs for HU were 12%, 49%, 48%, and 63%, respectively." (PMID 33663556, 2021). "The effect size of ABCG2 rs2231142 on urate is ~ 60% that of SLC2A9, yet the effect size on gout is greater." (PMID 32164793, 2020). "The aims of our study were to identify which variants of the SLC2A9 and SLC22A12 genes existed in a cohort of 250 individuals with primary hyperuricemia and gout, and at what frequency they existed." (PMID 32759716, 2020). "Our results for SLC2A9 SNPs and gout were also generally consistent with the recent updated meta-analysis, but we were able to pool additional effects of rs1014290, rs6449213 and rs7449213 in Caucasians and also rs6855911 in Asians." (PMID 33087043, 2020). "Therefore, SLC2A9 could be another promising target for lowering serum urate and the risk of gout." (PMID 33087043, 2020). "Genome-wide association studies (GWAS) have shown that many single nucleotide polymorphisms (SNPs) of ATP-binding cassette sub-family G member 2 gene (ABCG2) and the solute carrier family 2 member 9 (SLC2A9) are associated with serum urate and gout." (PMID 33087043, 2020). "Because genetic variants in urate transporter genes such as ABCG2, SLC2A9 and SLC22A12 are well known to cause SUA variation and gout, it is also possible that the SLC38A1/SNAT1 transporter is involved in urate or purine transport." (PMID 32238385, 2020). "We looked at genetic variants of genes encoding the major reabsorption proteins GLUT9 (SLC2A9) and URAT1 (SLC22A12) and their association with hyperuricemia and gout." (PMID 32759716, 2020). "A previous study showed that epistatic interactions between WDR1 and SLC2A9 regulated serum urate concentrations, suggesting the biological value of epistatic interactions in the pathogenesis of gout.." (PMID 32000861, 2020). "Consistent with previous reports, SLC2A9 and ABCG2 variants exerted the highest risk for gout among the whole group." (PMID 30626429, 2019). "We and others have performed GWASs of gout by comparing the genetic differences between gout cases and normouricaemia controls and have identified gout risk loci such as ABCG2 and SLC2A9: these are similar results to those from GWASs of SUA." (PMID 31289104, 2019). "Genome-wide association studies (GWASs) have explored many genes associated with gout, for instance, ABCG2, PKD2, SLC2A9, KCNQ1, SLC22A12 and SLC17A1 for gout disease among individuals of European descent." (PMID 30899057, 2019). "It suggested that genes which regulate inflammation and immunology such as NLRP3, except for genes which regulate urate homeostasis such as SLC2A9, were involved in the pathogenesis of gout." (PMID 29214547, 2018). "Odds Ratios (OR) for the associations with gout from the GWAS of gout were 1.54 (95% CI: 1.34; 1.78) for ABCG2 rs2231142 and 0.77 (95% CI: 0.68; 0.86) for SLC2A9 rs13111638." (PMID 30181573, 2018). "Hyperuricemia which plays a central role in the pathogenesis of gout, mostly relies on genetic factors, and the SLC2A9 gene appears to be the most important of them." (PMID 29615104, 2018). "Known genetic variants in SLC2A9 and ABCG2 were associated with urate and gout in a CKD cohort, with effect sizes for ABCG2 significantly greater in CKD compared to the general population." (PMID 30181573, 2018).
gout (continued). "Examples include evidence for a non-additive interaction of sugar-sweetened drinks consumption with a urate-associated variant of SLC2A9 in determining the risk of gout, and alcohol intake with LRP2 in determining the risk of hyperuricaemia and gout." (PMID 28566086, 2017). "A consistent finding of GWAS has been the observation that, while SLC2A9 variants are most strongly associated with hyperuricaemia, ABCG2 variants are more strongly associated with gout." (PMID 28566086, 2017). "A genetic risk score including ABCG2, SLC2A9, SLC22A12, SLC22A11 and SLC17A3 has also shown interaction with alcohol intake for gout risk." (PMID 28566086, 2017). "The aim of this study was to examine the role of SLC2A9 and ABCG2 variants in tophaceous disease in people with gout." (PMID 28270222, 2017). "Some of the previously reported gout associated loci (except ALDH16A1), including ABCG2, SLC2A9, GCKR, ALDH2 and CNIH2, were replicated." (PMID 28642574, 2017). "Among these genes, SLC22A12, CDC42BPG, and SLC2A9 were previously found to be related to serum uric acid levels or gout." (PMID 28410202, 2017). "Among the fourteen genes, six genes (ABCG2, SLC2A9, TRIM46, SLC17A1, A1CF and SLC17A4) affected both the elevation of the serum urate level and the development of gout from hyperuricemia and were identified as risk factors for gout." (PMID 28252667, 2017). "And 11 of the significant variants were from the gout associated loci (GCKR, SLC2A9, ABCG2, CNIH2, MYL2-CUX2 (ALDH2) and BCAS3)." (PMID 28642574, 2017). "Non-additive interaction between rs6449173 (in strong LD with rs12498742 and rs11942223) genotype at SLC2A9 and SSB consumption in control of serum urate and risk of gout has been reported." (PMID 26528330, 2015). "Previous GWASs have identified SLC2A9 and ABCG2 loci to be positively associated with serum uric acid levels and gout." (PMID 25634581, 2015). "Recent GWAS of SUA identified several genes including GLUT9/SLC2A9 and ABCG2/BCRP, which have been revealed to have associations with urate disorders such as renal hypouricemia and gout." (PMID 24366390, 2014). "Using European descent Czech populations, we performed a study of SLC2A9 and SLC22A12 genes previously identified as being associated with serum uric acid concentrations and gout." (PMID 25268603, 2014). "Two of these, SLC2A9 and ABCG2, have a very strong effect in gout (risk allele odds ratio (OR) >2.0) in multiple ancestral groups, whilst a third locus SLC17A1, has a weaker effect (OR <1.5)." (PMID 24360580, 2013). "Reduced renal excretion of urate is the most important cause of high plasma urate and gout, and SLC2A9 encodes a major urate transporter." (PMID 23422251, 2013). "Recent genome-wide association studies (GWAS) consistently showed that several single nucleotide polymorphisms (SNPs) in the solute carrier family 2 member 9 gene (SLC2A9 ) were associated with plasma urate concentration and the risk of gout." (PMID 23422251, 2013). "Certainly, gout case sample sets ascertained using such indirect criteria had lower effect sizes reported at SLC2A9, compared with sets using ARA criteria." (PMID 22541845, 2012). "Genome-wide association scans examining the genetic control of serum urate concentrations have identified two renal urate transporters - SLC2A9 and ABCG2 - that have a strong effect on gout risk in multiple ethnic groups." (PMID 22541845, 2012). "SNPs rs734553 and rs6855911, located in SLC2A9, and SNP rs2231142, known to be a missense polymorphism in ABCG2, were associated with gout (p = 5.6*10−7, p = 1.1*10−7, and p = 1.3*10−3, respectively)." (PMID 19890391, 2009). "Markers in SLC2A9 and ABCG2 genes are strongly associated with clinical manifestation of gout in the German MI Family Study." (PMID 19890391, 2009). "Furthermore, SLC2A9 expression has been identified in human articular chondrocytes, a key site of urate deposition in gout." (PMID 40093021, 2025).